TNF (tumor necrosis factor)
Diseases named in the same sentence as TNF in open-access papers (continued):
Sharing a sentence is not in itself a finding about the gene and the disease.
mucositis (continued). "We were unable to detect any correlation between IL-1, TNF-α, and IL-10 levels and mucositis." (PMID 20184737, 2010). "On molecular base, mucositis starts with the formation of reactive oxygen species (ROS), followed by the release of pro-inflammatory cytokines, as interleukin-1 beta (IL-1 β) and tumor necrosis factor (TNFα), resulting in infection, mucosal damage and cell damage consequently loss of their function." (PMID 37759230, 2023). "Mucositis reportedly consists of steps beginning with the formation of reactive oxygen species (ROS), progressing with the release of proinflammatory cytokines, such as tumor necrosis factor (TNF-α) and interleukin-1 beta (IL-1 β), resulting in mucosal damage, infection, and cell death." (PMID 27812611, 2016). "Previous studies have directly implicated the presence of TNF, IL-6, and IL-1β proinflammatory cytokines in the pathogenesis of a number of inflammatory diseases, such as inflammatory bowel disease (IBD), rheumatoid arthritis, sepsis, and most importantly, in mucositis." (PMID 22973511, 2012). "There was a statistically significant difference between the mucositis and mucositis FSO groups (p < .005), and between the mucositis and mucositis FSO‐R groups (p < .005) in terms of the TNF‐α values." (PMID 39554361, 2024). "Regarding the anti-inflammatory effect of DZN, in a separate study using mice as an animal model and 5-fluorouracil (5FU) to induce mucositis, the use of DZN resulted in the reduction of TNF-α levels, effectively mitigating inflammation." (PMID 38406792, 2023). "There were also significant differences in TNF-α levels in the large and small intestines between the ALA and Mucositis + ALA groups." (PMID 36290656, 2022). "Between the Control and Mucositis + ALA groups, there was a substantial difference in the levels of TNF-α in the small and large intestines." (PMID 36290656, 2022). "The TNF-α and IL-1β levels in sera and all tissues of animals in the Mucositis group were significantly higher when compared to Control, ALA and Mucositis + ALA groups (p < 0.05–0.0001)." (PMID 36290656, 2022). "We demonstrated that the protective effects of Lcr35 on 5-FU-induced mucositis were probably by triggering the Th1 immune response via downregulations of the cytokines IFN-γ and TNF-α." (PMID 33564301, 2021). "The role of reactive oxygen species and proinflammatory cytokines, such as tumor necrosis factor (TNF) and interleukin 1β, in conjunction with the innate immunity in the pathogenesis of mucositis have been extensively studied." (PMID 34071720, 2021). "PTX exhibits potent anti-inflammatory effects, directly inhibits TNFα, and reduces inflammation in multiple preclinical models, chemotherapy-induced intestinal (CPT-11) and oral (5-FU) mucositis." (PMID 28258409, 2017). "Patients were evaluated for mucositis according to WHO common toxicity criteria, and blood samples were drawn for inflammatory (IL-1, IL-6, IL-8, TNF-α) and anti-inflammatory (IL-10) cytokine levels before and during treatment." (PMID 20184737, 2010). "This transcription factor, which can also be directly activated by RT and/or CT, induces gene expression of proinflammatory cytokines such as interleukin-6 (IL-6), interleukin-1β (IL-1β), and tumor necrosis factor α (TNF-α), which are apparently increased in mucositis." (PMID 38473311, 2024). "In contrast, Dio efficaciously suppressed the expression of NF-κB downstream pro-inflammatory cytokines, including TNF-α, IL-6 and IL-1β in the ileums of CDDP-induced mucositis rats, and substantially promoted the production of the immunoregulatory mediators IL-10." (PMID 35457248, 2022). "However, TNF-α and IL-1β levels in the sera and all tissues reduced significantly in the Mucositis + ALA group compared to the Mucositis group (p < 0.05–0.0001)." (PMID 36290656, 2022).
mucositis (continued). "Despite the expression levels of some proteins involved in the inflammation response, such as TNF-α or IL-1β, partially correlate with mucositis process, their presence does not exclude others mucositis-independent inflammation events." (PMID 33028357, 2020). "In addition, we suggest that the DPP-4 inhibitors play a role in attenuating the severity of mucositis in the TNF-α dependent pathway, as the TNF-α expression is significantly down-regulated in the DPP-4i + 5-FU group." (PMID 31664952, 2019). "Other studies using MTX treatment in rats have shown induction of TNF-alpha, IL-1beta and macrophage inflammatory protein (MIP)-2 in the small intestine and these inflammatory cytokines likely mediate mucositis in the intestine and elsewhere in the gastrointestinal tract." (PMID 24444433, 2014). "A relationship between high levels of IL-6 and a high grade of mucositis at week 4 was found (p = 0.081), but no such relationship between IL-1, TNF-α, IL-8 or IL-10 level and mucositis grade was shown." (PMID 20184737, 2010). "They found an elevation in serum levels of cytokines IL-6, TNF-α and IL-1β which correlated with mucositis severity, and also showed that Amifostine did not reduce mucositis severity." (PMID 20184737, 2010). "Overall, while TNF-α levels alone may not conclusively differentiate between healthy and mucositis-affected sites in every context, they do appear to correlate with improvements in peri-implant health following therapeutic intervention." (PMID 41172495, 2025). "This lack of difference could indicate that TNF-α, while important in the inflammatory response, might not be a sensitive indicator of mucositis severity when comparing between groups." (PMID 41172495, 2025). "It suggests that while TNF-α is relevant in the inflammatory process, its levels alone may not be sufficient to distinguish between different stages or severities of peri-implant mucositis without considering other clinical and inflammatory markers." (PMID 41172495, 2025). "The reduced dose FSO (mucositis FSO‐R) was as effective as the full dose (mucositis FSO) in suppressing IL‐β and TNF‐α production, but was not as effective as the full dose in suppressing NF‐κB." (PMID 39554361, 2024).
meningitis (75 papers, 2006 to 2025). A disorder characterized by acute inflammation of the meninges of the brain and/or spinal cord. "TNF-α has also been shown to be a key cytokine in maintaining inflammation in other inflammatory diseases involving the CNS, such as some causes of meningitis and autoimmune encephalitis." (PMID 29190292, 2017). "Here, we confirmed that neonatal listeriosis also caused MG to produce high levels of TNF-a and IL-6, as reported in most neonatal human meningitis." (PMID 28335280, 2016). "Conversely, low TNF-α levels were found in the CSF of the same patients, as shown in meningitis caused by other viruses." (PMID 26569288, 2015). "Low levels of IL-1β, TNF-α or IL-6 in nasopharyngeal secretions were observed in children with recurrent episodes of acute otitis media, an important cause of meningitis." (PMID 26316174, 2015). "DNA from group B streptococcus, which causes neonatal sepsis and meningitis, also activates macrophages to produce TNF-α." (PMID 25472474, 2014). "Low levels of IL-1β, TNF-α and IL-6 in nasopharyngeal secretion were observed in children with recurrent episodes of acute otitis media, an important cause of meningitis." (PMID 21473761, 2011). "High levels of TNF-α, IL-6 and IL-1β are characteristic of meningitis processes and may be associated with disease severity and the occurrence of sequelae." (PMID 21473761, 2011). "Inflammatory mediators upregulated in zebrafish, including TNF, IL-1β, and G-CSF, parallel those found in human CSF during meningitis." (PMID 40609050, 2025). "The serum of the PM mice also displayed significantly elevated levels of the inflammatory cytokines TNF‐α, IL‐6, and IL‐1β in serum and brain homogenates for the meningitis group." (PMID 39887961, 2025). "Of the 13 measured, 11 (GM-CSF, IFNγ, IL-1α, IL-1Β, IL-2, IL-4, IL-6, IL-10, IL-12, IL-18, and TNF-α) exhibited higher concentrations in the saliva of pigs with meningitis and S. suis infection." (PMID 40284818, 2025). "To further explore the role of ZmpC in the development of meningitis, we determined the transcript levels of TNF-α, IL-8, and MMP-9 in the brain tissue of mice infected with CZ130302 and ΔzmpC." (PMID 39080654, 2024). "Between 2002 and 2012, tumor necrosis factor, interleukin‐6, early diagnosis, and meningitis were the most important outburst keywords with practical significance." (PMID 40626245, 2024). "C-reactive protein (CRP), tumor necrosisfactor-α (TNF-α), interleukin-1β (IL-1β), interleukin-6(IL-6), procalcitonin (PCT) are considered beingclosely implicated in the presence and progression ofpurulent meningitis." (PMID 39139150, 2024). "Zudem wurde eine aseptische Meningitis infolge der TNF-Blocker-Therapie mit Certolizumab diskutiert." (PMID 34586432, 2022). "Mehrere Einzelfallberichte einer aseptischen Meningitis unter verschiedenen TNF-Blockern sind in der Literatur beschrieben." (PMID 34586432, 2022). "The levels of inflammatory cytokines, including interleukin (IL)-1α, IL-1β, IL-6, and TNF-α, in brain tissues were significantly elevated after meningitis induction compared with those in normal controls." (PMID 35888118, 2022). "Nevertheless, neuroinflammation in meningitis can also be beneficial—the inactivation of TNF-α and IL-6 signaling in mice leads to increased lethality and neural deficits in surviving animals." (PMID 36028511, 2022). "Aseptic meningitis was probably related to markedly elevated inflammatory cytokines, such as IL-6, IL-2, interferon-γ, and tumor necrosis factor-alpha (TNF-α)." (PMID 35087588, 2022). "TNF-α expression has been shown to be upregulated in the brain after pneumococcal-induced meningitis." (PMID 34149363, 2021). "When comparing meningococcal-induced bacteremia and meningitis in patients, TNF-α levels were significantly higher in the latter." (PMID 34149363, 2021).
meningitis (continued). "We observed a lower TNFα concentration in the meningitis patient infected with serotype 6D which was, however, not significant upon univariate and multivariable analysis." (PMID 34620928, 2021). "The persistent activation of microglia leads to increased inflammatory protein TNF-α and IL-4 levels, 10 days after meningitis induction." (PMID 31901235, 2020). "In early meningeal infection, the pro-inflammatory cytokines interleukin (IL)-8, IL-1, tumor necrosis factor alpha (TNF-α), and IL-6 have been shown to be elevated." (PMID 30626412, 2019). "Some cytokines such as interleukin (IL)-1β, IL-6, IL-8, IL-10, interferon (IFN)-γ and tumor necrosis factor (TNF)-α have also been reported to be elevated in the CSF of TBM patients compared to other forms of meningitis." (PMID 29394269, 2018). "IL-6, IL-8, and TNF in CSF have in several studies been found to be elevated in meningitis and have even been proposed as biomarkers in CSF for bacterial meningitis." (PMID 30470234, 2018). "It is well established that inflammatory cytokines can contribute to BBB dysfunction in human disease, including studies of the BCSFB using albumin ratios in meningitis showing relationship to TNF- α, and cardiac surgery showing relationship to IL-6 and IL-8." (PMID 30186149, 2018). "The goal of the current study was to examine the interaction between IL-6 and TNFR1 as receptor for TNF-α and the innate immune response in vivo in a model of Streptococcus pneumoniae-induced meningitis." (PMID 27057100, 2016). "Here, we show for the first time that during meningitis cytokine and chemokine levels also positively correlate with the bacterial burden in the brain of wild-type mice (id est IL-6, TNF-α, IL-1β, IL-10, KC, and MIP-2)." (PMID 25958220, 2015). "Aseptic meningitis can be achieved via intracerebral TNFα injection with subsequent observation of leukocyte adhesion to and migration across the brain microvasculature as was described in our recent publication." (PMID 26507826, 2015). "Previous works have investigated the CSF levels of inflammatory cytokines and chemokines in patients with meningitis, such as IL-6, IL-1β, TNF-α, IL-10, chemokines of the CXC family (IL-8) and growth factors using immunoenzymatic methods." (PMID 26040285, 2015). "During the BM acute phase, an increase occurs in the expression of some cytokines, such as TNF-α and IL-6, which is useful for differential diagnosis with regard to other meningitis types such as aseptic or chronic meningitis." (PMID 26316174, 2015). "The concentrations of inflammatory cytokines such as TNF-alpha, IL-1beta and IL-8 in the CSF were also analysed in the differential diagnosis of meningitis but cannot be used in routine practice." (PMID 24885531, 2014). "TNF is an early response cytokine triggering an intense immune response and has been targeted in meningitis models as a therapeutic approach." (PMID 25409333, 2014). "TNF-α howed a contradictory result in the different studies, 2/6 of them demonstrated elevated levels of TNF-α during meningitis caused by S. pneumoniae, while 4/6 demonstrated the highest levels during NM." (PMID 23865742, 2013). "TNF-α is one of the most studied cytokine during BM and has been identified as a useful complementary tool to improve the diagnosis of meningitis, especially in cases where the CSF examination is inconclusive." (PMID 23865742, 2013). "In meningitis, both epithelia are exposed to inflammatory cytokines (TNF-α), to complement-derived products (e.g. C3a, C5a and sublytic doses of C5b9) as well as bacterial products such as lipopolysaccharide (LPS) and peptidoglycans (PGs)." (PMID 16948860, 2006). "When a panel of cytokines (including GM-CSF, IFNγ, IL-1α, IL-1β, IL-1ra, IL-2, IL-4, IL-6, IL-8, IL-10, IL-12, IL-18, and TNF-α) was measured in saliva from healthy pigs and in pigs with meningitis and S. suis infection, upregulation of several cytokines was observed in the diseased animals." (PMID 40284818, 2025).
meningitis (continued). "In our cases, Th1 response cytokines (IL-1 and TNFα) have been detected in Brucella-induced meningitis by immunohistochemistry, which could suggest a role of this type of response in brucellosis." (PMID 39199951, 2024). "Eighteen hours after the initiation of meningitis, the level of TNF-α was significantly inhibited by CPZ (the cytokine that was initially shown to be more strongly dependent on endocytosis), but the level of IL-6 was not, although IL-6 levels showed a decreasing trend." (PMID 36028511, 2022). "Microglia activation in turn would contribute to the increase in TNFα in hippocampal neurons of these rats, as occurs in rats with chronic hyperammonemia and hepatic encephalopathy, in meningitis, in dorsal horn neurons and the spinal cord, or in propofol-induced neurotoxicity." (PMID 35740285, 2022). "TNF-α is another important early-response cytokine and is related to a fatal outcome in meningitis." (PMID 34437417, 2021). "In mpneumococcal-induced meningitis, both microglia and astrocyte recognize S. pneumoniae components through the NOD2 receptor, causing increased nuclear translocation of NF-κB and release of IL-6 and TNF-α from both cell types." (PMID 34149363, 2021). "Compared to serotype 10A, on multivariable analysis controlling for age and HIV status, we found serotype 18A to be associated with higher concentration of TNFα concentration (coef: 6.22, HDI: 2.08, 10.31) in the CSF of meningitis patients (Bayesian R2 = 0.40)." (PMID 34620928, 2021). "To date, the strategy of using adjunctive TNF-α antagonists instead of corticosteroids to prevent CNS-TB-associated PR/IRIS and improve outcomes has only been explored with thalidomide in children with stage 2 and 3 TB meningitis." (PMID 33120751, 2020). "Furthermore, the molecular pathways of calycosin-anti-meningitis were revealed, including suppression of NF-kappa B, Toll-like receptor, TNF signaling pathways." (PMID 33031061, 2020). "While there is promising data for TNF-α, IL-6, and IL-8 as diagnostic biomarkers in meningitis, CSF shunt infections are a biofilm rather than planktonic infection which skews the host immune response." (PMID 30626412, 2019). "BBB opening controlled by TNF is necessary for the development of meningitis." (PMID 30837977, 2019). "In addition it was shown that TNF-alpha is responsible for increased BBB permeability in E.coli induced meningitis." (PMID 24852285, 2014). "High levels of the pro-inflammatory cytokines such as interleukin 1 beta (IL-1 beta), interleukin 6 (IL-6) and tumor necrosis factor alpha (TNF alpha), were detected in the cerebro-spinal fluid (CSF) of patients with meningitis, which is typical of the severe inflammation of the brain." (PMID 23874613, 2013). "Since in meningitis, TNF in CSF is mainly derived from infiltrating cells, the extent of leukocyte infiltration might have determined TNF levels in the four strains." (PMID 17428319, 2007). "Our previous study showed that the meningitis-associated E. coli strain PCN033 could infect astrocytes U251, induce rapid inflammatory responses, and promote the expression of many pro-inflammatory mediators such as IL-1β, IL-6, IL-8, TNF-α, MCP-1, and MIP-2." (PMID 33985523, 2021). "Overall, the analysis of cytokine concentrations indicated that CSF from meningitis patients with serotypes 6D and 23A had low levels of IL-6 whereas those with serotypes 22A, 7F and 15B/C had high levels of IL-8 and with serotype 18A had high concentrations of TNFα." (PMID 34620928, 2021). "Interestingly, we found elevated TNF and C1q levels in the hippocampal region after 10 days of meningitis induction, suggesting the possibility of A1-reactive astrocytes induction after experimental meningitis." (PMID 31901235, 2020).